METTL3 (methyltransferase 3, N6-adenosine-methyltransferase complex catalytic subunit)
Diseases named in the same sentence as METTL3 in open-access papers (continued):
Sharing a sentence is not in itself a finding about the gene and the disease.
osteoporosis (continued). "Furthermore, early growth response 1 (EGR1), a transcription factor of METTL3, can promote osteoclast differentiation and osteoporosis development by regulating the METTL3/m6A/Chi3l1 axis." (PMID 39769202, 2024). "METTL3 has also been found to modulate the progression of BMSCs and osteoporosis." (PMID 38538596, 2024). "Moreover, METTL3 specifically overexpressed in mouse osteoblasts and further confirmed that METTL3 can inhibit the progression of senile osteoporosis." (PMID 38538596, 2024). "Our results confirmed the significant role of METTL3 in osteoblast aging and suggested that METTL3 could be a potential therapeutic target for senile osteoporosis." (PMID 38538596, 2024). "However, Lin Shuibin’s team concentrated more on how METTL3-mediated m6A RNA methylation regulates bone marrow mesenchymal stem cells’ fate and osteoporosis directions." (PMID 36970605, 2023). "First, METTL3 was found to be downregulated in osteoporosis." (PMID 37047394, 2023). "METTL3, the key methyltransferase of m6A, was observed to regulate the fate of osteoporosis." (PMID 35718942, 2022). "METTL3 is reported to be involved in the regulation of bone biology and osteoporosis." (PMID 34645714, 2021). "Besides, METTL3 is found to be downregulated in human osteoporosis and the ovariectomized mouse model." (PMID 34094986, 2021). "Considering the pathologic effect of Mettl3 deletion in triggering osteoporosis, we questioned whether Mettl3 overexpression is capable to enhance skeletal health or prevent bone disorders." (PMID 30429466, 2018). "In addition, this study emphasizes the importance of m6A modification in osteoblasts in senile osteoporosis, which provides new insights into the potential molecular mechanism of METTL3 regulating osteoblast senescence and the development of strategies for the treatment of senile osteoporosis." (PMID 38538596, 2024). "Therefore, our study supports the regulatory role of m6A and METTL3 in senile osteoporosis." (PMID 38538596, 2024). "In contrast, overexpression of METTL3 could rescue osteoporosis in mice." (PMID 32850871, 2020). "Although it has been reported that alterations in METTL3 modulate the osteogenic lineage commitment and differentiation of BMSCs and are involved in osteoporosis, the role of m6A modification in osteoblast differentiation in an inflammatory environment remains unclear." (PMID 31892163, 2019). "In this context, a recent study suggests that experimental depletion of Mettl3 in mesenchymal stem cells could lead to the development of osteoporosis in a mice model, while its upregulation provides protection against osteoporosis triggered by estrogen deficiency." (PMID 31426393, 2019). "Studies have shown that the expression levels of METTL3 and METTL14 are significantly decreased in the bone tissue of osteoporosis patients." (PMID 39779466, 2025). "Molecular mechanism studies have shown that Runx2 mRNA is an m6A‐methylated target of METTL3 at its 3′‐UTR, METTL3 mediates m6A methylation of Runx2, enhancing cellular stability and potentially rescuing the characteristics of osteoporosis." (PMID 39779466, 2025). "In vivo and in vitro experiments showed that Cpd-564 could inhibit the expression of METTL3, thereby inhibiting osteoblast senescence and delaying the occurrence and progression of osteoporosis, which is a promising new method for the prevention of osteoporosis." (PMID 40989884, 2025). "METTL3 overexpression promoted the expression and m6A modification of DUSP14, HDAC5, and Nfam1, which has been reported to slow down the onset of osteoporosis." (PMID 38665846, 2024). "Cell fate of BMSCs in mice is disrupted by METTL3 or METTL14 deletion, leading to osteoporosis pathological characteristics including decreased bone mass and accumulated marrow adiposity." (PMID 38665846, 2024). "It was discovered that the expression of METTL3 and METTL14 and the overall m6A level were decreased in the bone tissues of three patients with osteoporosis." (PMID 37202385, 2023).
osteoporosis (continued). "Moreover, although METTL3 targets Runx2, VEGF and different signaling pathways to promote osteogenic differentiation, it remains controversial whether METTL3 is a potential therapeutic target for osteoporosis, as METTL3 also activates osteoclasts and then increases bone resorption." (PMID 34993198, 2021). "Interestingly, METTL3 has been suggested as a potential treatment target in osteoarthritis, whereas FTO has been suggested as a target in osteoporosis." (PMID 39629934, 2025). "Consistent results for METTL3 and METTL14 were obtained in osteoporosis animal models." (PMID 38665846, 2024). "M6A methyltransferase METTL3 and demethyltransferase FTO involves in the delicate process between adipogenesis differentiation and osteogenic differentiation, which is important for the pathological development of osteoporosis." (PMID 31998240, 2019). "Serum ELISA results showed a significant upregulation in N-MID-OT and a significant downregulation in PINP, while the downregulation of β-CTx was not statistically significant, suggesting that METTL3 primarily affects bone-forming ability in senile osteoporosis." (PMID 38538596, 2024). "Interestingly, the results revealed a notable decrease in METTL3 mRNA expression specifically in the bone tissues of patients with senile osteoporosis, while no significant change was found in the expression of other genes." (PMID 38538596, 2024). "Interestingly, FTO expression in the bone is up-regulated during aging and osteoporosis, while the expression of METTL3 is not affected by age." (PMID 32110378, 2020). "Consequently, METTL3 and METTL14 may serve as potential targets for osteoporosis treatment." (PMID 39779466, 2025). "Furthermore, researchers have discovered that METTL3 may be involved in high glucose and palmitic acid (HGPA)-induced osteoporosis via activating the ASK1/p38 signaling pathway, in which they noticed that METTL3 knockdown prevented HGPA-induced activation of ASK1/p38 signaling." (PMID 37215218, 2023).
viral infection (41 papers, 2019 to 2026). "Research has found that the absence of METTL3 in CD4+T cells impairs the function of TFH cells, leading to a significant reduction in germinal center (GC) response in METTL3 deficient mice after acute viral infection." (PMID 40248704, 2025). "Ctrl SMARTA CD4+ T cells exhibited vigorously proliferation post viral infection, whereas METTL3-deficient cells displayed a delayed proliferation." (PMID 33637761, 2021). "Moreover, clinical data corroborates these findings, showing that METTL3 overexpression is associated with increased susceptibility to viral infections and autoimmune conditions." (PMID 40196133, 2025). "We next examined whether METTL3 deficiency in CD4+ T cells affects GC formation during viral infection." (PMID 33637761, 2021). "Consequently, the GC reactions were significantly compromised in METTL3-deficient mice in response to acute viral infection." (PMID 33637761, 2021). "We propose that METTL3 depletion activates antiviral signaling primarily by modifying the expression of cellular mRNAs encoding antiviral regulator and effector genes, which happens independently of viral infection (and, as we show, even before virus infection)." (PMID 40214229, 2025). "Consistent with this possibility, the present results show that individuals with prior viral infection exhibit a distinct oral signature: they show both an epigenetic-immunomodulatory change (decreased METTL3) and lower plaque accumulation." (PMID 40917458, 2025). "Quantitative analysis confirmed that METTL3 shifted from predominantly nuclear to cytoplasmic localization when co-expressed with M protein and during the course of viral infection." (PMID 41325422, 2025). "We further examined the localization pattern of endogenous METTL3 upon BPIV3 infection and found that it predominantly resided within the nucleus in uninfected cells, whereas virus infection redirected endogenous METTL3 to cytoplasmic inclusion bodies." (PMID 41325422, 2025). "Concurrently, Western blot indicated that METTL3 expression was significantly downregulated in a time- and dose-dependent manner after viral infection." (PMID 40802811, 2025). "The existence of additional regulatory phosphorylation sites on METTL3 during viral infection remains an open question." (PMID 40802811, 2025). "As a core m6A methyltransferase, METTL3 plays a multifaceted role in viral infection, including the regulation of viral replication and participation in innate immune responses." (PMID 40802811, 2025). "This is supported by the demonstration of targeted recruitment of METTL3/14 to specific regulatory RNAs under stress and viral infection, resulting in functional alterations in the stability and translation of these RNAs." (PMID 41267684, 2025). "These researches displayed different expression patterns of METTL3 with different viral infections and cell types." (PMID 39759074, 2024). "Further, the inhibitors of methyltransferase-like 3 (METTL3), which is responsible for catalyzing N6-methyladenosine (m6A) modification on mRNA, were described as potential inhibitors of viral infections." (PMID 39273355, 2024). "Consistently, severe growth defects observed in the cellular KO phenotype of METTL3 underscore METTL3’s essential role in maintaining cellular homeostasis during development, cancer growth, and viral infections, including SARS-CoV-227–29." (PMID 37609305, 2024). "Upon viral infection, METTL3 enhances the nuclear export and translation of antiviral signaling molecule mRNAs, such as IRF3, and promotes the induction of IFN-β and inflammatory cytokines against viral infection." (PMID 38957616, 2024). "For example, in HIV and Enterovirus infection, viral infection can increase writer (METTL3/14 (methyltransferase 3/14)) and decrease eraser (FTO (fat mass and obesity-associated protein) or ALKBH5 (alkB homolog 5)) levels and thus promote viral replication." (PMID 37325513, 2023).
viral infection (continued). "Viral infection enhances the expression of METTL3/14 and DF1–3 at an early stage and decreases their expression at the late stage; however, the expression of ALKBH5 and FTO is consistently suppressed during infection." (PMID 37325513, 2023). "The resulting blockade of the p65 pathway enhances viral replication, whereas the recruitment and interaction between DDX5 and METTL3 can be further exploited and enhanced by viral infections." (PMID 35897696, 2022). "Many lines of evidence suggest that METTL3 plays important roles in several diseases such as cancers and viral infection." (PMID 35571106, 2022). "Accumulating studies have demonstrated that METTL3 as a potential therapeutic target for cancers and virus infection." (PMID 35571106, 2022). "It is worth mentioning that ablation of METTL3 resulted in more severe defects in TFH cells (21.4-fold change) than TH1 cells (1.9-fold change) upon acute viral infection." (PMID 33637761, 2021). "Upon knockdown of METTL3, the WT Fiber construct showed a decrease in splicing efficiency, similar to that observed during viral infection." (PMID 33243990, 2020). "Substantial evidence links METTL3 to various immune dysfunctions, such as the suppression of antiviral immunity during viral infections and the disruption of immune tolerance in conditions like autoimmune diseases, myeloid leukemia, skin cancers, and anticancer immunotherapy." (PMID 40196133, 2025). "Given that lactylation upregulates METTL3 expression and enhances its RNA-binding capacity, it is plausible that lactylation may potentiate METTL3-driven immune suppression during viral infection." (PMID 40720394, 2025). "It will be interesting to explore whether METTL3 and other members of the m6A RNA modification pathway are regulated by PIAS1-mediated SUMOylation and the associated impacts on RNA modification, viral infection, and host defense." (PMID 38236021, 2024). "Therefore, the search for inhibitors of METTL3 or those that interfere with METTL3 activation represents one of the novel strategies to cure viral infections through activation of innate immunity." (PMID 39273355, 2024). "The role of N6-methyladenosine in the virus–host interaction and viral infection progression allows for suggesting that METTL3-mediated activation of M6A may be considered a promising target for antiviral therapy." (PMID 39273355, 2024). "Notably, METTL3-mediated m6A modifications play an important role in modulating the innate immune response to viral infections, including the sensing of invading RNAs and the regulation of transcripts involved in innate immune signaling." (PMID 39759074, 2024). "Viral infection induces a host cell stress response whereby m6A modification might favor translation by changes in the subcellular localization of METTL3." (PMID 36786625, 2023). "Similarly, the deletion of METTL3 or YTHDF2 has been reported to stabilize IFNB1 in an m6A-dependent manner following viral infection, leading to subsequent suppression of the virus reproduction in host cell." (PMID 35120571, 2022). "Moreover, many lines of evidence suggest that METTL3 plays important roles in various diseases such as cardiovascular diseases, diabetes, and viral infection." (PMID 35571106, 2022). "Using an adoptive transfer model, we found that METTL3-deficient CD4+ T cells showed a delayed differentiation and a slower proliferation upon acute viral infection, although they were activated normally as shown by expression of the surface markers via both in vivo and in vitro assay." (PMID 33637761, 2021). "In our study, we found that the interaction of DDX5 and METTL3 was enhanced by viral infection." (PMID 33909701, 2021). "Consequently, IFN-β expression is markedly suppressed during wild-type virus infection, whereas the export-deficient M-K258R mutant fails to deplete nuclear METTL3, leading to preserved m6A modification and elevated IFN-β expression." (PMID 41325422, 2025).
viral infection (continued). "Thus, it seems that METTL3 may function as a rapid epigenetic sensor of microbial challenge in a host whose immune set-point has been recalibrated after viral infection." (PMID 40917458, 2025). "METTL3 dysregulation may result in the emergence of a varietyof diseases ranging from cancer to cardiovascular and neurologicaldisorders beyond contributing to viral infections." (PMID 36692498, 2023). "Finally, based on our investigation, targeting cytoplasmic METTL3 or METTL3 activity maybe a new strategy to ameliorate anti-viral innate immune response and cure patients who suffered from viral infections." (PMID 33707441, 2021). "A recent investigation conducted in human fibroblasts indicated that genes stimulated by interferon after virus infection could be induced once METTL3 and YTHDF2 were repressed, which showed that the m6A modification of murine IFNβ mRNA could accelerate its degradation." (PMID 32029706, 2020). "Oxidative stress, DNA damage, or viral infection are known to alter TERC trafficking, and METTL3 participates in these processes." (PMID 41456942, 2026). "The use of a small molecule inhibitor (STM2457) that targets the m6A writer protein, METTL3, was shown to diminish infectious viral particle release and sense-strand-derived viral transcripts in vitro, indicative that it may be therapeutically efficacious early in viral infection." (PMID 39861913, 2025). "To investigate the impact of this mechanism on viral infection, we co-transfected METTL3&14 and MDA5 plasmids and found that METTL3&14 partially suppressed the antiviral immune benefit of MDA5." (PMID 39347580, 2024). "Previous studies have demonstrated an interaction between DDX5 and METTL3, as well as an interaction between METTL3 and METTL14 to form a m6A writer complex upon virus infection." (PMID 38182816, 2024). "Knockdown of METTL3, METTL14, and YTHDF2 significantly increased viral infection and replication, while knockdown of ALKBH5 decreased viral infection and replication." (PMID 35465335, 2022). "Coincidentally, the interaction of DDX5 and METTL3 has also been found in macrophage lipid uptake, which indicated that METTL3 is the pivotal target of DDX5 in cellular development and viral infection." (PMID 33909701, 2021). "Methyltransferase-like 3 (METTL3) is the principal catalytic enzyme responsible for m6A deposition, and its pharmacological inhibition has emerged as a potential therapeutic strategy for cancer and viral infections." (PMID 42210692, 2026). "Notably, another report using SARS-CoV-2 and HCoV-OC43 showed that METTL3 and YTHDF1-3 promote both virus replication in VeroE6 cells and their depletion suppresses viral infection." (PMID 41019992, 2025). "Measurements of periodontal parameters revealed a reduction in the periodontitis group with prior COVID-19 infection compared to those without previous viral infection, along with a significant decrease in salivary METTL3 expression (p = 0.0003)." (PMID 40917458, 2025). "METTL14 collaborates with METTL3 in regulating the replication of various viruses, including HCV, HDV, IAV, HSV-1 and HIV, suggesting a supporting role for METTL14 in these viral infections." (PMID 38551978, 2024). "In the absence of METTL3 followed by viral infection resulted in the modular and highly specific hundreds of IFN-stimulated genes (ISGs) production." (PMID 33330128, 2020). "A recent study conducted in human foreskin fibroblasts indicated that inhibition of the m6A writer METTL3 and reader YTHDF2, led to an increase in the induction of interferon-stimulated genes after virus infection and showed that the m6A of murine Ifnb mRNA accelerated its mRNA degradtion." (PMID 31015515, 2019). "Our study finds that METTL3 can boost cellular protein translation even without viral infection." (PMID 40802811, 2025). "However, it remains unknown whether small-molecule inhibitors targeting METTL3, such as STM2457, contribute to multiple viral infections and host immune responses." (PMID 38957616, 2024).
viral infection (continued). "Furthermore, expression of interferon-stimulated genes such as MX1 and OAS1 was blocked downstream of poly(I:C) transfection by JAK inhibition but not induced by viral infection or METTL3 knockdown." (PMID 33243990, 2020).